MEIS3P2 (Meis homeobox 3 pseudogene 2)
Gene: Protein-coding gene on chromosome 17 (20,589,058 to 20,590,700, forward strand). Ensembl gene ENSG00000188013.
Subcellular location: Nucleus
Gene Ontology:
Molecular function: DNA-binding transcription activator activity, RNA polymerase II-specific; RNA polymerase II cis-regulatory region sequence-specific DNA binding; DNA binding
Biological process: angiogenesis; animal organ morphogenesis; brain development; embryonic pattern specification; eye development; hemopoiesis; positive regulation of cell population proliferation; positive regulation of transcription by RNA polymerase II; regulation of DNA-templated transcription
Cellular component: nucleus
Homologues: Orthologues: macaque MEIS3 (95% identical), rat Meis3 (86% identical), guinea pig MEIS3 (86% identical), dog MEIS3 (86% identical), mouse Meis3 (85% identical), rabbit MEIS3 (82% identical), tropical clawed frog meis3 (71% identical), zebrafish meis3 (61% identical), Drosophila melanogaster hth (54% identical), Caenorhabditis elegans unc-62 (44% identical), Drosophila melanogaster exd (19% identical), Caenorhabditis elegans ceh-60 (18% identical), and 3 more. Paralogues in human: MEIS3 (94% identical), MEIS2 (68% identical), MEIS1 (65% identical), PKNOX2 (37% identical), PKNOX1 (35% identical), PBX1 (22% identical), PBX2 (22% identical), PBX3 (21% identical), PBX4 (20% identical), TGIF1 (17% identical), TGIF2 (13% identical), TGIF2LX (12% identical), and 1 more.